ENSG00000269533 (novel transcript)
Gene: Protein-coding gene on chromosome 19 (57,389,884 to 57,419,994, forward strand). Ensembl gene ENSG00000269533.
Genetic constraint (gnomAD): Loss-of-function variants: 7 observed, 9.28 expected, observed/expected ratio (o/e) 0.75, 90% interval 0.43 to 1.41. That is too few expected variants to judge how well the gene tolerates losing a copy. Missense variants: 129 observed, 144.31 expected, observed/expected ratio (o/e) 0.89, 90% interval 0.77 to 1.03. Synonymous variants: 49 observed, 49.57 expected, observed/expected ratio (o/e) 0.99, 90% interval 0.79 to 1.25.